LGALS3 (galectin 3)
Diseases named in the same sentence as LGALS3 in open-access papers (continued):
Sharing a sentence is not in itself a finding about the gene and the disease.
tumor (continued). "It has been proven that Src kinase-dependent caveolin-1 (Cav1) phosphorylation increased tumor cell migration in a Galectin-3-dependent manner." (PMID 29254179, 2017). "Tumor pieces were immersed for 6 h in media supplemented with glycosylated IFNγ alone or with galectin-3 antagonists." (PMID 28986561, 2017). "Galectin antagonists increased strongly CXCL9 expression in tumor xenografts and human biopsies, supporting the notion that galectin-3 lattices in the tumor ECM are the important players of IFNγ retention." (PMID 28986561, 2017). "Analyzing the epithelial fraction of tumor resection specimens, the Galectin 3 (Gal3) cell count in T2 cases was significantly higher than in T1 cases (median 241 cells/mm2 and 97 cells/mm2, respectively, p < 0.001)." (PMID 29284429, 2017). "For example, mouse cells that lack Tsc2 produce more of a protein called galectin-3, which appears to help blood vessels and tumours to grow in cancers." (PMID 28695825, 2017). "The level of galectin-3 secretion was negatively correlated with the final expansion factor of the T cells at the end of the MLTC performed with these tumor cells." (PMID 28401257, 2017). "Both Galectin-1 and Galectin-3 are located in the extracellular space and have similar functions, such as lattice formation and regulation of tumour adhesion, invasion and migration." (PMID 28701735, 2017). "Analysis of galectin-3 secretion by ELISA showed that most tested tumor cell lines produced galectin-3 to variable amounts." (PMID 28401257, 2017). "The possible anti-tumour mechanism is that rGal3C disrupts Galectin-3-integrin clustering on the cell surface, resulting in suppression of integrin/FAK/SRC pathway and subsequent down-regulation of NDRG1 expression." (PMID 28701735, 2017). "The use of galectin-3-depleted tumor supernatants and the use of a galectin-3 knock-out tumor line enabled us to specifically eliminate tumor-derived galectin-3 in our culture system." (PMID 28401257, 2017). "Another phenomenon that was found in some specimens (2/19) was the higher expression of Galectin-3 in the tumor frontier." (PMID 29254179, 2017). "Taking together these data, we conclude that, in this mouse model, inhibition of galectin-3 reduces the tumor growth by boosting IFNγ intratumoral activity." (PMID 28986561, 2017). "The intercellular adhesion molecule 1 (ICAM-1), the vascular cell adhesion molecule 1 (VCAM-1), E-selectin and galectin-3 have been reported to be involved in the interaction of tumor and endothelial cells." (PMID 29100413, 2017). "Galectin-3 regulated the expression of VE-cadherin, and has been reported to play an essential role during the formation of VM in tumor cells." (PMID 28264434, 2017). "Among Galectins, Galectin-3 is one of the best studied, which mediates multiple processes of tumor growth." (PMID 29254179, 2017). "We have previously shown another role for extracellular galectin-3 that is related to surface receptor mobility: its ability to impede the lytic activity and the secretion of cytokines of galectin-covered human tumor-infiltrating lymphocytes." (PMID 28986561, 2017). "This study shows that tumor-secreted galectin-3 hijacks IFNγ in the tumor microenvironment, reducing the induction of a chemokine gradient and thereby T-cell recruitment into the tumor bed." (PMID 28986561, 2017). "Galectin-3 and -8 support the vascularization process in the tumor microenvironment binding to integrin αvβ3 and activated leucocyte cell adhesion molecule (ALCAM), respectively." (PMID 29258207, 2017). "The accumulating of Galectin-3 in the tumor cell cytoplasm stimulates the tumor cell to become more invasive and provoke distant metastasis." (PMID 28264434, 2017). "The phylogenetic highly conserved protein Galectin 3 (Gal3) is an important mediator between cell differentiation and tumor immunity and contributes to the regulation of macrophage polarization." (PMID 29284429, 2017).
tumor (continued). "We have found a relationship among galectin-3, NF-κB, hypoxia and nutrient deprivation, and common stressing conditions within the tumor microenvironment." (PMID 27242966, 2016). "Conversely, it was demonstrated that galectin-3 expression induced by NF-κB transactivation led to a more invasive phenotype of tumor cells, which developed larger tumors as compared to those found in galectin-3−/− mice." (PMID 27242966, 2016). "Here the authors show that Galectin-3 expressed by tumour cells inhibits LFA-1 on cytotoxic lymphocytes, impairing immunological synapse formation, IFNg secretion, and target cell killing." (PMID 27447355, 2016). "In our study we orthotopically injected 4T1 tumor cells in Balb/c Lgals3−/− and Lgals3+/+ mice strain." (PMID 27526676, 2016). "Its promoter region, as well as its first exon, exhibits a high content of CpG islands, indicating that epigenetic mechanisms also control galectin-3 expression, as observed during malignant transformation and tumor progression." (PMID 27242966, 2016). "Galectin-3 functions as a modulator of cell-cell adhesion, cell-matrix interactions, tumor angiogenesis and metastasis, immune response and apoptosis." (PMID 27191983, 2016). "What is the role of non-γ-carboxylated TAM ligands (Tubby, TULP-1, Galectin-3) in the tumor microenvironment?" (PMID 27916840, 2016). "Galectin-3C was reported to act as a dominant negative inhibitor of extracellular gal-3 carbohydrate binding and to reduce tumor growth, motility, invasion and angiogenesis through inhibition of galectin-3." (PMID 27835877, 2016). "It is established that cell surface glycans such as mucins and integrins can interact with β-galactoside-binding lectins such as galectin-3 for forming molecular lattices and plays key roles in the extracellular modulation of tumor progression." (PMID 27382435, 2016). "We determined the expression level of NICD1 and stemness factors, such as NANOG, OCT4 and SOX-2 in tumor sections prepared galectin-3 overexpressing A2780 cells." (PMID 27626163, 2016). "Several reports have demonstrated that galectin-3 interaction with its glycoconjugate ligands increased cancer homotypic aggregation to form a tumor micro-emboli and cancer cell heterotypic adhesion to the blood vascular endothelium." (PMID 27526676, 2016). "Using ultrasonography (USG) we were able to find an increased growth of 4T1 tumor cells in Lgals3−/− mice (line’s slope = 99,19) in comparison with Lgals3+/+ mice (line’s slope = 91,74)." (PMID 27526676, 2016). "Extracellular galectin-3 is involved with cell migration (tumor cell, endothelial cell, and leukocyte migration) and the formation of vessels." (PMID 27242966, 2016). "Here, we will present some examples of how galectin-3 coordinates cellular responses in two critical hallmarks of cancer, tumor cell motility (see Galectin-3 Promotes Tumor Migration) and angiogenesis (see Galectin-3 in Tumor Vasculature)." (PMID 27242966, 2016). "Galectin-3 and its glycoconjugate ligands prolong the tumor cell survival in the circulation by promoting tumor cell homotypic aggregation, thus facilitating their dissemination and preventing anoikis." (PMID 27526676, 2016). "Although galectin-3 modulates important functions in immunocompetent and inflammatory cells, its role in tissues involved with tumor dissemination as lymph nodes and hematopoietic bone marrow is poorly explored." (PMID 27526676, 2016). "As compared to galectin-3 expression, galectin-9 expression was quite low either in H1299 monolayers or tumor spheres." (PMID 25669973, 2015). "Galectin-3 (Gal-3) is upregulated in many tumor cells extra- and intracellularly and therefore a target for tumor diagnostic and therapy." (PMID 26213980, 2015). "In tumor cells, galectin-3 expression often appeared mutually exclusive with expression of galectin-1 or -9, since its expression was reduced when expression of another type of galectin was present." (PMID 26066796, 2015).
tumor (continued). "Galectin-3 single positive cells were strongly correlated with galectin-1/3 double positive cells within the tumor stroma (R = 0.693, p<0.0001)." (PMID 26066796, 2015). "Strong correlations were found between galectin-9 single positive cells and galectin-3/9 double positive cells both in the epithelial and in the stromal tumor compartment (R = 0.706, p<0.0001; R = 0.680, p<0.0001, respectively)." (PMID 26066796, 2015). "In this study we showed that the markedly necrotic areas around which galectin-3 is overexpressed in tumor cells as confirmed, as confirmed by the hypoxiprobe-1 staining in the same areas." (PMID 26222311, 2015). "Other authors did not confirm these results, but it was suggested that the expression of galectin-3 in cytoplasm of the epithelial cells correlates positively with tumor progression." (PMID 26042506, 2015). "The present study aimed to evaluate the role of a cell cycle regulator like cyclin D1 in these tumours along with assessment of other well established PTC markers like galectin-3, HBME-1, CK19." (PMID 25907675, 2015). "Many galectins including galectin-1 and galectin-3 have also shown a correlation with tumor development and can be used as markers of potential cancerous growth." (PMID 25730388, 2015). "There is a dynamic regulation of galectin-3 and its ligands in response to the tumor microenvironment." (PMID 26222311, 2015). "LGALS3BP is a large oligomeric, highly glycosylated protein composed of ≈90 kDa subunits that was originally identified as a tumor-secreted antigen and as a ligand of the lactose-specific S-type lectin, galectin-3 (formerly Mac-2)." (PMID 26219351, 2015). "Galectin-1 and -9 were both expressed by tumor cells in 11% of samples, while 84% expressed galectin-3." (PMID 26066796, 2015). "Although the molecular mechanisms critical for pro-tumor activation of SS-TAMs by apoptotic cells require further evaluation, the present work highlights several candidate oncogenic players such as galectin-3 and the TYRO/AXL/MER axis." (PMID 25702581, 2015). "Despite the low expression of galectin-3 in most malignant tumor areas tumor cells surrounding necrotic areas are found to express more galectin-3." (PMID 26222311, 2015). "Galectin-3, a β-galactoside-binding lectin, is a cell adhesion molecule involved in the regulation of tumor progression." (PMID 25373317, 2015). "Gas6, protein S and galectin-3, the ligands for Mer, have been also described to be frequently overexpressed in tumor tissues of NSCLC, suggesting that Mer receptor is continuously activated in NSCLC via autocrine and/or paracrine mechanisms." (PMID 25826078, 2015). "If this was the case, galectin-3 was mainly expressed in the center of the tumor fields, while galectin-1 and -9 were expressed at the invasive border." (PMID 26066796, 2015). "Weak and positive tumor cell galectin-3 expression were correlated with increased and decreased tumor invasion, respectively (p = 0.012)." (PMID 26066796, 2015). "Accumulated evidence indicates that galectin-3 is closely involved in tumor cell proliferation, transformation, migration, invasion, and metastasis." (PMID 26273429, 2015). "As for other NCRs, two other binding partners for LAG-3 have been described which are expressed in the tumor microenvironment: the Liver sinusoidal endothelial cell lectin (LSECtin) and Galectin-3 (Gal-3)." (PMID 26347741, 2015). "The mRNA and protein levels of galectin-3 in tumor sphere-generated cells were detected by RT-qPCR and Western Blot." (PMID 25669973, 2015). "The tumor cells also expressed galectin-3 and focally expressed CK19, additional markers that have been shown to be positive in PTC." (PMID 26351607, 2015). "High levels of galectin-3 expression were found in tumor areas surrounding necrotic tissue as well as in lung micro metastases." (PMID 26222311, 2015).
tumor (continued). "Galectin-3 is expressed by macrophages, fibroblasts, activated T cells, eosinophils, epithelial and tumor cells, inducing anti-apoptotic signaling." (PMID 26066796, 2015). "Increased tumor angiogenesis is another common effect of galectin-3 on cancer progression and metastasis, and some modified heparins have previously been shown to have anti-angiogenic properties." (PMID 26160844, 2015). "Experimental and clinical studies have revealed that the galectin-3 expressed in tumor cells is important at different stages of tumorigenesis, including malignant cell transformation, invasion and metastasis." (PMID 25373317, 2015). "Recent studies have shown that increased concentrations of circulating galectin-3 promote dissemination of tumour cell metastatic spread to remote sites." (PMID 26160844, 2015). "In situ hybridization confirmed that galectin-3 transcription was in fact increased in the tumor cells from hypoxic regions." (PMID 26222311, 2015). "Beside preoperative evaluation due to the tumor's dimension several studies have been performed to find markers able to distinguish malignant from benign follicular tumors in the thyroid, with Galectin-3 being one of the most effective." (PMID 26604924, 2015). "Strong tumor cell galectin-3 expression was often present either at the invasive border or center of the tumor fields." (PMID 26066796, 2015). "After the A549 cells overexpressed galectin-3 and were cultured in tumor sphere medium, an apparent sub-population grown as tumor spheres was identified." (PMID 25669973, 2015). "Despite these evidences, our understanding on the role of extracellular galectin-3 present at the tumor milieu is still limited." (PMID 24982845, 2014). "We detected expression of galectin-3 by fibroblasts, immune cells and tumor cells in single-cell tumor suspensions." (PMID 24658839, 2014). "Interactions between cancer associated carbohydrate Thomsen-Friedenreich antigen (TF-Ag) and endothelium-expressed galectin-3 (Gal-3) have been identified as the leading molecular mechanism initiating tumor/endothelial cell adhesion in several types of cancer." (PMID 24675526, 2014). "Galectin-3 functions, however, seem first related with tumor cell survival in stressed microenvironments (hypoxic and serum-deprived), such as those found in pseudopalisades." (PMID 25369297, 2014). "Corroborating our observations on the areas covered by functional vessels, secretion of VEGF was augmented in tumors with galectin-3 from either tumor or stromal origin." (PMID 24421272, 2014). "In conclusion, regardless its source (tumor parenchyma or stroma), galectin-3 plays a role in the organization of the tumor microenvironment." (PMID 24421272, 2014). "MUC1 activity is also known to contribute to Ttzm resistance, and a high circulating level of galectin-3 in patient serum is related to tumor progression." (PMID 25499743, 2014). "This lectin is found in the tumor stroma, suggesting a role for microenvironmental galectin-3 in tumor progression." (PMID 24982845, 2014). "Despite the low number of papers published on the direct effects of Mgat5 activity on galectin-3 function, both proteins are increased during tumor progression and deserve attention as suitable targets in malignant diseases." (PMID 24982845, 2014). "We next exploited the model system to further address what the selective advantage is of having tumor cells-expressing galectin-3 and if it is critical that the origin of galectin-3 is a tumor or a stromal cell." (PMID 24421272, 2014). "This extracellular galectin-3-mediated modulation of tumor cell motility deserves further investigation in different models." (PMID 24982845, 2014). "These high-throughput arrays revealed for the first time that enhanced synthesis and secretion of cytokines like VEGFA and galectin-3 participate in the regulation of tumor angiogenesis and contribute to CXCR7-mediated metastatic phenotype." (PMID 25341042, 2014).
tumor (continued). "In this review, we aim to examine recent data regarding the extracellular functions of galectin-3 in some steps of tumor progression and metastasis." (PMID 24982845, 2014). "This work reinforces the idea that extracellular galectin-3 plays a role in the organization of tumor microenvironment." (PMID 24982845, 2014). "Taking into account in vitro data showing a lower binding of malignant cells onto lung tissue of galectin-3 KO mice, the authors suggested the involvement of stromal cell-derived galectin-3 on tumor cell adhesion to the metastatic target." (PMID 24982845, 2014). "Compared to tumor cells harboring cleavable galectin-3, tumor cells transfected with cleavage resistant galectin-3 showed reduced tumor growth in athymic nude mice and diminished angiogenesis." (PMID 24982845, 2014). "Sialylation was reported to regulate interaction between galectin-3 and ligand in tumor cells and the mechanisms are crucial in regulating adhesive and de-adhesive events in the invasive capacity of metastatic cells." (PMID 24589677, 2014). "Intracellular galectin-3 expression was significantly higher in tumor cells versus fibroblasts (p < 0.05)." (PMID 24658839, 2014). "With regard to intracellular galectin-3 expression, the majority of fibroblasts, immune cells and tumor cells expressed galectin-3." (PMID 24658839, 2014). "Galectin-3 is known to be chemoattractant to endothelial cells and to stimulate neovascularization in vivo, therefore contributing to tumor angiogenesis, an essential step for metastatic spreading." (PMID 24563633, 2014). "Most primary HCC tumor tissues showed significantly upregulated galectin-3 expression relative to normal tissues." (PMID 25260879, 2014). "In conclusion, this review aims to describe the processes of tumor progression and metastasis involving extracellular galectin-3 and its expression and regulation." (PMID 24982845, 2014). "Previous studies have shown that galectin-3 expression levels are correlated with tumor proliferation in cancer." (PMID 25260879, 2014). "In cancer biology, galectin-3 has been reported to play a role in aggregation processes that lead to tumor embolization and survival." (PMID 25161713, 2014). "There are multiple lines of evidence pointing to the relevance of galectin-3 in malignant cell transformation, tumor growth, anoikis resistance, apoptosis inhibition, angiogenesis, cell adhesion, cell motility, and cell invasion." (PMID 24982845, 2014). "Altogether, when galectin-3 was present in both tumor compartments and stromal compartments, tumors grew faster than any other combinations." (PMID 24421272, 2014). "Binding of galectin-3 to N-glycans has been connected to multiple cellular processes including cell adhesion and migration, immune cell function, inflammation, and neoplasia." (PMID 24130706, 2013). "Galectin-1 and galectin-3 are highly expressed in tumor tissues and galectin-3 confers high metastatic potential." (PMID 23251263, 2013). "Further experiments indicated that galectin-3 expression is related with the induction of a proangiogenic tumor environment." (PMID 24764473, 2013). "Since it was shown that removal of the tumor decreased serum galectin-3 concentrations in other cancers, tumor tissues are likely to produce and secrete galectin-3 in sera." (PMID 23625538, 2013). "Injection of CRD domain to tumor bearing mice significantly reduced the tumor volume confirming that only full-length galectin-3 is required for cancer progression." (PMID 23625538, 2013). "We will show evidence for fluctuations in the expression of a specific tumor marker, namely galectin-3." (PMID 24764473, 2013). "Specifically, they suggest that the Thomsen-Friedenreich (TF) glycoantigen (a β-galactoside) on tumour cells leads to clustering of galectin-3 on the surface of endothelial cells and transient adhesion." (PMID 22272201, 2012).